MTOR (mechanistic target of rapamycin kinase)
Diseases named in the same sentence as MTOR in open-access papers (continued):
Sharing a sentence is not in itself a finding about the gene and the disease.
cancer (continued). "Concerning Metformin, many mechanisms of anti-cancer activity have been proposed, such as modulation of immunological and/or anti-inflammatory responses, inhibition of mTOR, and inhibition of the insulin signals and glucose synthesis via respiratory-chain complex I blockage." (PMID 36139522, 2022). "The mTOR pathway regulates cancer cell proliferation and tumor angiogenesis." (PMID 36304306, 2022). "The anabolic demands of proliferating cancer cells require adaptation of metabolic profile, increasing glycolytic rate (Warburg effect), which may be attributed to mTOR pathway." (PMID 35163615, 2022). "Because of the relationship between mTOR pathway and cancer immunity, we hypothesized that genetic mutations in mTOR pathway may affect the cancer immunity microenvironment and predict the response to ICI treatment for cancer patients." (PMID 35642038, 2022). "Consequently, mTOR has been recognized as a key target for the treatment of cancer, especially for treating cancers with elevated mTOR signaling due to genetic or metabolic disorders." (PMID 36109789, 2022). "Noteworthy is the fact that, besides being involved in VM development, the MAPK, PI3K/Akt/mTOR and PI3K/Akt/Gsk signaling pathways are also implicated in different cellular functions relevant to cancer progression, such as cell proliferation, adhesion, migration, metabolism, and survival." (PMID 35887002, 2022). "IR-increased GSVA score of mTORC1 signaling was suppressed by adding entinostat, which may be supported by previous reports that entinostat suppresses cancer cell growth via PI3K/AKT/mTOR signaling inhibition." (PMID 36555180, 2022). "However, high expression of mTOR is favorable to the sensitivity of cancer cell lines to chemotherapy." (PMID 35655775, 2022). "The Akt/mTOR signaling pathway plays a vital role in cancer survival and progression." (PMID 35662690, 2022). "Recent evidence found that anti-cancer drugs targeting mTOR slow AD progression by reducing iron accumulation, suggesting that selective anticancer drugs might have a modulating effect on AD pathophysiology." (PMID 36199128, 2022). "Excessive lactate released by reprogramming cancer cells' metabolism affects immunological responses through extracellular acidification, serving as an energy source by migrating among various cell populations and blocking the mTOR pathway in immune cells." (PMID 36419156, 2022). "Overall, greater comprehension of the mechanism that leads to targeting of hyperactive AKT/mTOR pathway may provide valuable insights to help design new strategies that will enhance the impact of betulinic acid in cancer chemoprevention." (PMID 36615262, 2022). "Notably, both the mTOR complexes play a central role in orchestrating metabolic reprogramming in cancer cells, and the alterations in mTOR-related signaling pathways probably dictate metabolic adaptations of dormant cells." (PMID 35158815, 2022). "The lack of survival prediction for patients with non-ICI treatment was also validated in 763 advanced cancer patients from TCGA, indicating the specific predictive ability of the mutations in mTOR pathway genes for ICI treatment efficacy." (PMID 35642038, 2022). "Inhibition of PI3K/Akt/mTOR pathway could drive cell death process of cancer cells and could slow the progress of tumors in vivo." (PMID 36180880, 2022). "We found that mTOR-activated MEFs and human cancer cells generally produce more exon-skipping transcripts in the transcriptome, posing multifaceted functions in the proteome in the context of protein stability, functional domain changes, and post-translational modification site changes." (PMID 36293270, 2022).
cancer (continued). "Eukaryotic translation initiation factor 4E binding protein 1 (EIF4EBP1) encodes the 4EBP1 protein, a negative regulator of mRNA translation and a substrate of the mechanistic target of rapamycin (mTOR), whose function and relevance in cancer is still under debate." (PMID 35228525, 2022). "Cancer cell size and mTOR signaling was diminished in tumors propagated in Camkk2-null mice." (PMID 35741020, 2022). "The sustained over-activation of mTOR signaling will lead to increased levels of cellular metabolism, promoting continued cell growth and proliferation and even cell immortalization, which directly or indirectly induces cancer." (PMID 36612173, 2022). "Upregulation of the PI3K/AKT/mTOR pathway, which regulates multiple cellular functions (e.g., tumorigenesis, proliferation, differentiation, and apoptosis), has been demonstrated in many cancers." (PMID 35174643, 2022). "Rapamycin has been approved by the FDA for mTOR driven cancers." (PMID 36328247, 2022). "The PI3K/AKT/mTOR pathway is the most commonly disrupted in cancer." (PMID 35402264, 2022). "Overall, the decision to use different immunosuppressive regimens derived from several aspects, like specific clinical necessities (using mTOR inhibitors in patients with previous history of cancer), specific immunological background (pre-transplant PRA value), or protocols of research." (PMID 35109826, 2022). "Moreover, our results uncover a reciprocal interaction of NOP56 and mTOR signaling and suggest that combined inhibition of NOP56/mTOR is a rational strategy to combat KRAS-mutant cancer." (PMID 35039048, 2022). "Our previous experiments indicated that FC101′s anti-cancer activity may be directly related to its inhibition of the mTOR signaling pathway." (PMID 36428475, 2022). "Furthermore, the metabolic plasticity of cancer cells allows them to trigger mTOR-independent mechanisms to compensate for the inhibited mTOR activity, thereby allowing the cells to acquire sufficient nutrients for growth and proliferation." (PMID 35078427, 2022). "This preliminary data suggests that a combination of polyamine biosynthetic and mTOR pathway inhibitors may have greater effect in inhibiting cellular processes and pathways that promote cancer cell proliferation." (PMID 36135836, 2022). "Furthur studies have found that THSD7A may impact the biological processes of cancer cells via multiple tumor-related pathways, such as mTOR, Wnt, and MAPK." (PMID 36506585, 2022). "Deletion of mTOR blunted immune cell function and down-regulated the PD-L1 expression in cancers." (PMID 35642038, 2022). "Previous studies have shown the importance of the mTOR pathway in the pathogenesis of cancer." (PMID 35558559, 2022). "Compounds that inhibit both PI3Ka and mTOR, which may offer great potential in cancer therapy, are designed by many companies, including Pfizer, and their PI3K/mTOR dual inhibitory activities are currently being investigated for clinical trials." (PMID 35335262, 2022). "Some patients initially respond to tyrosine kinase inhibitors (TKI) but ultimately develop resistance: cancers acquire TKI-desensitizing EGFR mutations or activate compensatory signals, including WNT/β-catenin, the mechanistic target of rapamycin mTOR, and AKT signaling to drive cancer recurrence." (PMID 35461372, 2022). "Excessive activity of the PI3K/AKT/mTOR pathway may lead to the development of benign and malignant tumors and overgrowth." (PMID 35187600, 2022). "In addition, PI3K-Akt-mTOR signaling genes in cancer pathways were significantly decreased by the SMAPoTN treatment in the HFD group." (PMID 36290662, 2022). "This suggests that prospective studies using mTOR inhibitors could be evaluated in symptomatic immune granulomatosis, especially since mTOR inhibitors also have anti-cancer properties." (PMID 35740604, 2022).
cancer (continued). "The PI3K/v-akt murine lymphoma viral oncogene homolog (AKT)/mTOR signaling cascade serves many (patho)physiological functions and is one of the major cancer signaling pathways playing a critical role in regulating cancer cell growth, survival and proliferation." (PMID 35326659, 2022). "Additionally, the inhibition of mTOR via rapamycin treatment altered the metabolism of lymphoma cells, decreasing the glycolytic state and provoking regression of Warburg effect in cancer cells." (PMID 35163615, 2022). "Importantly, irradiation induces mTOR phosphorylation and activation, which contributes to cancer metastasis." (PMID 35326517, 2022). "Excessive activity of the PI3K/AKT/mTOR pathway due to PTEN deficiency may lead to the development of benign and malignant tumors and overgrowth." (PMID 35187600, 2022). "There are currently no approved therapies to target the PI3K/AKT/mTOR pathway in patients with cancers having germline PTEN mutations and CS or other forms of PHTS." (PMID 36039910, 2022). "mTOR pathway was well recognized as simulators for cancer malignancy in multiple cancers." (PMID 35642038, 2022). "mTOR is a protein complex with increasing therapeutical potential as a target in cancer." (PMID 35216092, 2022). "Similar to the results of previous studies using mTOR inhibitors, PD-L1 expression in cancer cells could be reduced by lomitapide treatment, suggesting its tumor-intrinsic effects." (PMID 35831271, 2022). "With numerous inhibitors of PI3K and mTOR already FDA approved, an obvious next step would be to investigate whether co-targeting AR and either PI3K or mTOR results in synergistic anti-cancer activity." (PMID 35650195, 2022). "The mainly PI3K/AKT/mTOR pathway is alive at the level of aerobic glycolysis in cancer cells." (PMID 36034776, 2022). "The PI3K/AKT/mTOR pathway is a well-known survival pathway that is dysregulated in many cancers." (PMID 35887151, 2022). "In addition, it was reported that LMO4 promoted the invasion and proliferation of cancer by activating the PI3K/Akt/mTOR signalling pathway." (PMID 36347834, 2022). "It indicated that targeting individual components of this pathway, such as PI3K, phosphoinositide-dependent kinase-1 (PDK-1), Akt, and mTOR (mammalian Target of Rapamycin), may be a possible cancer therapy technique." (PMID 36160435, 2022). "The mTOR pathway is frequently overactivated and promotes mRNA translation and cancer progression in various types of cancers, and is a promising therapeutic target for cancer therapy." (PMID 35304469, 2022). "Besides the TME- and immune-related pathways, the pan-cancer survival network enriches further signaling pathways that have high cross-cohort relevance for survival such as mTOR-signaling." (PMID 35106465, 2022). "Studies have reported that the Akt/mTOR pathway plays a crucial role in essential cellular activities, such as cell proliferation, growth, and metabolism and found that it is commonly activated in human cancers." (PMID 36105365, 2022). "Napabucasin (NB), a phytochemical compound, has been reported as potential anti-cancer agent, however, Akt and mTOR targeting mechanisms remain unclear." (PMID 36180880, 2022). "RPTOR is a key component in mTOR pathway, a cell-signaling pathway commonly deregulated in human cancer, which plays roles in mRNA translation, autophagy, cell growth and immune responses (it restricts proinflammatory and promotes an anti-inflammatory response)." (PMID 35163587, 2022).
cancer (continued). "The PI3K/AKT/mTOR pathway is aberrantly dysregulated in certain cancers such as TNBC; therefore, direct inhibition of the PI3K/AKT/mTOR pathway in combination with PARPIs could be an effective strategy to overcome PARPI resistance." (PMID 35785170, 2022). "Importantly, lactate secreted in a tumor microenvironment (TME) inhibits the immune response and favors the establishment of an acidic pH that counteracts the efficacy of many anti-cancer agents (including immunotherapies and mTOR inhibitors)." (PMID 35626081, 2022). "Metabolic reprogramming is primarily regulated in cancer cells by the serine/threonine kinase mTOR." (PMID 35204484, 2022). "High levels of phosphorylated m-TOR expression in HPV-related cancers can serve as a prognostic marker for poor chemotherapy response and overall patient survival, and mTOR inhibitors, such as rapamycin, are currently being tested as potential therapeutic targets." (PMID 36145459, 2022). "Due to the frequency of alterations in the PI3K/AKT/mTOR signaling pathway, its role in promoting cancer cell growth and invasion, and integrative analysis data, targeting of this signaling cascade has a robust rationale with wide-ranging therapeutic implications." (PMID 35326708, 2022). "We have partitioned this multi-component review into different sections in which we summarized landmark research-works which highlighted betulinic acid mediated regulation of JAK/STAT, VEGF, EGF/EGFR, TRAIL/TRAIL-R, AKT/mTOR and ubiquitination pathways in the inhibition of cancer." (PMID 36615262, 2022). "Activation of PI3K/AKT/mTOR, an important pathway regulating autophagy, is prevalent in many cancers and may be responsible for reducing cytoprotective autophagy and deregulated proliferation." (PMID 35847878, 2022). "In addition to acting in the PI3K/Akt pathway, the highly conserved protein kinase known as mTOR is also essential for controlling tumor cell motility and cancer spread." (PMID 38094222, 2022). "In conclusion, these observations suggest that the mTOR signaling pathway is a key regulatory step in ROS-induced autophagy, but the exact molecular mechanism between ROS-induced autophagy and mTOR signaling in cancer remains to be further investigated." (PMID 36676047, 2022). "Multiple GSEA analysis of G6PD showed that mTOR signaling, Notch signaling, and cancer pathways were mainly enriched in the high expression group, whereas other metabolic pathways, such as drug metabolism, fatty acid metabolism, and tryptophan metabolism were enriched in the low expression group." (PMID 35938165, 2022). "Affecting the kinase domain of mTOR with novel small molecules to suppress both mTORC1 and mTORC2 activity might improve the efficacy of mTOR suppression in cancer therapy." (PMID 36109789, 2022). "For instance, quercetin, the key component of Huangqi, could inhibit metastasis of cancer cells by blocking Akt/mTOR/c-Myc signaling pathway to suppress RPS19-activated EMT signaling." (PMID 36313348, 2022). "The previous studies have exhibited that significant PI3K/AKT/mTOR axis is significantly altered in cancer and targeting this axis with multiple inhibitors can modulate a variety of cellular processes such as cell proliferation, autophagy, apoptosis, angiogenesis, EMT, and chemoresistance." (PMID 35402264, 2022). "New data are linking mTOR to intestinal homeostasis and cancer." (PMID 36293326, 2022). "A high concentration of mTOR is also observed in many types of cancers, suggesting that increased expression of the mTOR gene may be one of the important factors supporting tumor development." (PMID 36513976, 2022).
cancer (continued). "In contrast, mTOR is upregulated in a variety of cancer types." (PMID 36077039, 2022). "Moreover, Pi3k–Akt–mTor signalling, which also regulates metabolic reprogramming in cancer, is activated as judged by the phosphorylation of mTORC1 proteins such as S6K1." (PMID 35460513, 2022). "Interestingly, stromal cells can also secrete growth factors activating the MAPK and Pi3K/AKT/mTOR, leading to resistance of cancer cells." (PMID 36093296, 2022). "Moreover, high expression of a protein kinase enzyme (Akt) has been reported to be involved in tumor invasion and metastasis therefore, inhibiting the mTOR pathway can be an efficient anti-cancer strategy for several human malignancies." (PMID 35145999, 2022). "Several recent studies have discovered that the accumulation of BCAAs in cancer cells due to the reduction in catabolism may enhance the activity of mTOR signaling pathway and promote cancer progression." (PMID 35461343, 2022). "The PI3K/Akt/mTOR axis is related to antiapoptosis and proliferation in cancer cells." (PMID 36354662, 2022). "In addition, mTOR activity is upregulated in human cancer and can accelerate tumorigenesis and development through various mechanisms, such as angiogenesis, promotion of growth factor receptor signaling, and suppression of autophagy." (PMID 36077620, 2022). "Abnormal activation of the PI3K/AKT/mTOR signaling pathway has been found in a number of cancers affects nearly 50% of malignant tumors, including HCC, and mediates cancer cell proliferation, migration, invasion, angiogenesis and other pathological processes in tumor cells." (PMID 35903690, 2022). "Thus, AMPK, as an mTOR and lipogenesis inhibitor, as well as the one ensuring viability through metabolic reprogramming in cancer cells, prolongs the life of cancer cells." (PMID 36291824, 2022). "The positive correlation between mTOR staining intensities and tumor grades suggests that the mTOR expression profile may be a potential index/biomarker for evaluating cancer aggressiveness." (PMID 36077039, 2022). "Leucine was involved in 11 metabolic pathways, such as central carbon metabolism in cancer, aminoacyl tRNA biosynthesis, mammalian target of rapamycin (mTOR) signaling pathway, biosynthesis of amino acids, protein digestion, and absorption between the positive and negative ion modes." (PMID 36199104, 2022). "PI3K/AKT/mTOR pathway derangement occurs in 80–95% of Type I or endometrioid endometrial carcinomas, with PTEN being the most commonly mutated gene in this type of cancer." (PMID 35408777, 2022). "It has been reported that mTOR pathway is critical in stemness of cancer cells as well." (PMID 36284084, 2022). "AKAP1 involves in mTOR pathway regulation and cancer growth." (PMID 36672755, 2022). "Additionally, we used in silico tools to investigate gene expression profile of mTOR in various types of cancers and normal tissues." (PMID 35082928, 2022). "Taken together, antioxidant therapy is expected to be used in cancer treatment, which may result in different anti-cancer efficacy based on the mTOR pathway activation status." (PMID 35642038, 2022). "Drugs targeting the PI3K/Akt/mTOR signaling pathway may repress the tumor cell’s survival pathway and activate autophagy and apoptosis in cancer cells." (PMID 35293266, 2022). "Collectively, these previous observations advance our understanding of the role mTOR pathway may play in metabolism reprogramming that is essential for generation of immune effector cells in cancer microenvironment." (PMID 35642038, 2022). "mTOR is known to facilitate cancer cell growth and can be inhibited by AMPK." (PMID 35298869, 2022). "Therefore, it is likely to be crucial for tumorigenesis when TXNIP expression is downregulated in cancers with constitutive PI3K/Akt/mTOR pathway activation." (PMID 36366411, 2022).